EGLN1 (egl-9 family hypoxia inducible factor 1)
Diseases named in the same sentence as EGLN1 in open-access papers (continued):
Sharing a sentence is not in itself a finding about the gene and the disease.
endothelial dysfunction (3 papers, 2024 to 2025). In vascular diseases, endothelial dysfunction is a systemic pathological state of the endothelium (the inner lining of blood vessels) and can be broadly defined as an imbalance between vasodilating and vasoconstricting substances produced by (or acting on) the endothelium. "Intriguingly, EGLN1 inhibition attenuated high glucose-induced endothelial dysfunction by activating autophagy pathways, as evidenced by increased LC3-II/LC3-I ratios and decreased P62 levels." (PMID 41087486, 2025).
familial erythrocytosis (3 papers, 2016 to 2022). "A review of the literature on recently reported mutations in patients with non-MPN erythrocytosis, highlighted the role of some known genes associated with familial erythrocytosis, such as EPO, HBB, VHL EGLN1, EPAS1, and EPOR." (PMID 36290845, 2022).
Familial erythrocytosis type 3 (3 papers, 2022 to 2025). "Interestingly, mutations in EGLN1 are linked to two different autosomal dominant blood disorders, familial erythrocytosis-3 and high altitude adaptation hemoglobin, reflecting an important role specific to blood cells." (PMID 39713361, 2024).
lung adenocarcinoma (3 papers, 2021 to 2025). A carcinoma that arises from the lung and is characterized by the presence of malignant glandular epithelial cells. "EGLN1 overexpres-sion was associated with worse survival in cervical squamous cell carcinoma (CESC), pancreatic adenocarcinoma (PAAD), and neuroblastoma (NB), while EGLN3 was linked to poor survival in CESC, lung adenocarcinoma (LUAD), and kidney cancers." (PMID 40464184, 2025).
Parkinson disease (3 papers, 2019 to 2024). A progressive degenerative disorder of the central nervous system characterized by loss of dopamine producing neurons in the substantia nigra and the presence of Lewy bodies in the substantia nigra and locus coeruleus. "In a study of age-related neurodegeneration, EGLN1-HIFa signaling contributed to mitochondrial stress-induced neurotoxicity by ATP13A2 regulation in Parkinson’s disease (PD)." (PMID 38649851, 2024).
chronic mountain sickness (2 papers, 2017 to 2022). A pathological condition resulting from chronic exposure to hypoxia at high altitude. "Moreover, in preclinical chronic mountain sickness, an hypermethylation of EGLN1 has been reported to diminish PHD2 expression and thereby enable transcription of HIF-1α." (PMID 36091390, 2022).
high altitude pulmonary edema (2 papers, 2016 to 2017). "High altitude pulmonary edema (HAPE) susceptibility is associated with EGLN1 polymorphisms, we hypothesized that HAPE-susceptible (HAPE-S, had HAPE episode in past) subjects may exhibit abnormal HIF1α levels in normoxic conditions." (PMID 27210110, 2016).
multiple endocrine neoplasia type 2 (2 papers, 2014 to 2016). Multiple endocrine neoplasia type 2 (MEN2) is a multiple endocrine neoplasia, a polyglandular cancer syndrome characterized by the occurrence of medullary thyroid carcinoma (MTC), pheochromocytoma (PCC), in one variant, primary hyperparathyroidism (PHPT). "The kinase signalling subgroup, includes characteristic mutations in REarranged during Transfection (RET) in Multiple Endocrine Neoplasia type 2 (MEN2), Neurofibromatosis type 1 (NF1), transmembrane protein 127 (TMEM127), MYC associated factor X (MAX), EGLN1 (PHD2), KIF1 and IDH1." (PMID 27535829, 2016).
nasopharyngeal carcinoma (2 papers, 2022 to 2024). A carcinoma arising from the nasopharyngeal epithelium. "In nasopharyngeal carcinoma, contrary to our results, the level of IHC-stained EGLN1 was detected to be higher compared to that in normal tissues, with its expression correlating with larger tumor size." (PMID 38928200, 2024). "However, there is no consensus on the regulation of EGLN1 and its mechanism of action on nasopharyngeal carcinoma (NPC)." (PMID 35517429, 2022).
triple-negative breast carcinoma (2 papers, 2017 to 2024). An invasive breast carcinoma which is negative for expression of estrogen receptor (ER), progesterone receptor (PR), and human epidermal growth factor receptor 2 (HER2). "Importantly, the human ortholog of EGL-9 (EglN1) has previously been implicated as a cysteine sensor in the context of triple negative breast cancer (TNBC)." (PMID 38349720, 2024).
type 2 diabetes (2 papers, 2024). "Roxadustat exposure led to induction of HIF target gene mRNAs for GLUT1, HK2 (encoding hexokinase 2), MCT4 (encoding monocarboxylate transporter 4) and HIF-P4H-2 (also known as PHD2 or EGLN1) in myotubes from donors with NGT, with a blunted response in myotubes from donors with type 2 diabetes." (PMID 38814443, 2024). "Treatment with roxadustat led to induction of HIF target gene mRNAs for GLUT1 (also known as SLC2A1), HK2, MCT4 (also known as SLC16A4) and HIF-P4H-2 (also known as PHD2 or EGLN1) in myotubes from donors with NGT, with a blunted response in myotubes from donors with type 2 diabetes." (PMID 38814443, 2024).
viral infection (2 papers, 2023 to 2024). "Disruption of Egln1 in mice and zebrafish attenuates host innate antiviral immune responses, and Irf3 prolyl hydroxylation-deficient mice are more susceptible to lethal viral infections." (PMID 38670937, 2024). "It appeared that the dynamics of IRF3 hydroxylation during viral infection was due to changes in the hydroxylase activity of EGLN1 during viral infection." (PMID 38670937, 2024). "Furthermore, mice and zebrafish with Egln1 deletion, treatment with the EGLN inhibitor FG4592, or mice carrying an Irf3 P10A mutation are more susceptible to viral infections." (PMID 38670937, 2024). "To further understand the reason, we then examined whether the hydroxylase activity of EGLN1 was altered in the process of viral infection by using HIF1α hydroxylation as an indicator." (PMID 38670937, 2024). "To determine whether the enhancement of antiviral responses under normoxia is mediated by EGLN1, we examined the effect of EGLN1 on immune responses upon viral infection." (PMID 38670937, 2024). "Notably, the interaction between IRF3 and EGLN1 was stable during viral infection." (PMID 38670937, 2024). "To further validate that EGLN1 mediates the phenotypic difference between WT and Irf3_P10A mice in response to viral infection, we used FG4592 (10 mg/kg) to block EGLN1 activity in WT and Irf3_P10A mice and then challenged them with VSV." (PMID 38670937, 2024). "To further determine whether Egln1 specifically modulates antiviral responses in response to viral infection, rather than having a broad transcriptional role, we performed genome-wide RNA sequencing (RNA-seq) analysis using Egln1+/+ and Egln1−/− MEF cells infected without or with VSV." (PMID 38670937, 2024). "Thus, the strategy to knock out Egln1 in mice was reliable and successful, and the deletion of Egln1 exhibits no obvious effects on the expression of Ifn-β or Isg15 in the lung, spleen, and liver without virus infection." (PMID 38670937, 2024).
altitude sickness (1 paper, 2019). Multiple symptoms associated with reduced oxygen at high altitude. "Genomic studies have identified robust signals of positive selection across EPAS1, EGLN1, and PPARA, that are associated with hemoglobin levels, which likely protect the Sherpa from altitude sickness." (PMID 31555147, 2019).
Alzheimer disease (1 paper, 2025). A progressive, neurodegenerative disease characterized by loss of function and death of nerve cells in several areas of the brain leading to loss of cognitive function such as memory and language. "We asked whether activation of the hypoxia-inducible factor (HIF) pathway via genetic deficiency of HIF prolyl 4-hydoxylase-2 (HIF-P4H-2; also known as PHD2/EGLN1) could be an Alzheimer’s disease–modifying therapy using transgenic amyloid precursor protein (APP)/presenilin 1 (PS1) female mice." (PMID 40609789, 2025).
Chronic Lymphocytic Leukemia (1 paper, 2022). "In this study, we found that HIF-PH encoded by EGLN1 is a potential therapeutic target for chronic lymphocytic leukemia and its inhibitor, molidustat, has considerable killing effect on CLL cell lines." (PMID 35745653, 2022).
clear cell ovarian cancer (1 paper, 2023). "The loss of EGLN1 which encodes prolyl hydroxylase domain-containing protein 2 inhibited the proliferation of clear cell ovarian cancer cells." (PMID 36798826, 2023).
diabetic nephropathy (1 paper, 2022). "Moreover, apoptosis, another classical marker of ROS damage in diabetic nephropathy, was reduced not only in DMOG-treated mIMCD3 cells exposed to high glucose concentrations in hypoxia but also in DMOG-treated Leprdb/db mice and diabetic Egln1+/- mice." (PMID 35164902, 2022).
epilepsy (1 paper, 2021). A brain disorder characterized by episodes of abnormally increased neuronal discharge resulting in transient episodes of sensory or motor neurological dysfunction, or psychic dysfunction. "There are 2 genes (NFE2L2 and EGLN1) related to these features in the CvsE group and there are studies in the literature suggesting that these genes are related to epilepsy." (PMID 34588521, 2021). "Interestingly, we observed that when compared to the normal controls, the expression of some identified genes was only significantly altered either in Epilepsy (EGLN1, ELAVL4, and NFE2l2) or Hemorrhage (USP22, EYA1, SIX1, OAS3, SRMS) groups." (PMID 34588521, 2021). "Interestingly, downregulation of EGLN1, ELAVL4, NFE2L2 KCNK18 genes was only detected in epilepsy-related (CvsE) gene list." (PMID 34588521, 2021).
lentivirus infection (1 paper, 2024). Virus diseases caused by the Lentivirus genus. "In HIF1β−/− H1299 cells, overexpression of wildtype EGLN1 (EGLN1-WT), but not of EGLN1-H313A by lentivirus infection, enhanced VSV-induced IFN-β expression." (PMID 38670937, 2024).
oral cavity tumor (1 paper, 2024). "The oral cavity tumor results reflected data without stratification, namely, we observed a significant decrease in EGLN1 levels compared to normal tissues (p = 0.0032), while EGLN3 and HIF1A mRNA levels were higher (p < 0.0001; p = 0.0012)." (PMID 38928200, 2024).
ovarian carcinoma (1 paper, 2021). A malignant neoplasm originating from the surface ovarian epithelium. "As an example, inhibition of Egl nine homolog 1 (EGLN1) through the pan-EGLN1 inhibitor FG-4592 was found to selectively reduce the viability of HIF1A-high or ARID1A-mutant human ovarian cancer cell lines." (PMID 33809714, 2021).
thrombosis (1 paper, 2015). "Both Pitta and high altitude natives had the genotype in EGLN1 that was HA associated and VWF that was linked to protection from thrombosis." (PMID 26047609, 2015). "A combination of derived EGLN1 allele (HAPE associated) and ancestral VWF allele (thrombosis associated) was significantly high in Kapha group compared to Pitta (p < 10–5)." (PMID 26047609, 2015).
tumor (134 papers, 2009 to 2025). "As shown, EGLN1 was associated with clinical stages, tumor formation, self-renewal, and differentiation." (PMID 35517429, 2022). "The H374R mutation is also associated with recurrent PGL, suggesting a crucial role for PHD2/EGLN1 as a tumor suppressor gene that is similar to VHL missense mutations seen in type 2 VHL disease, i.e., high risk of PCC/PGL." (PMID 36699028, 2022). "Furthermore, it was shown that loss of PHD2 (EGLN1) impairs tumor growth and suppresses the pro-metastatic activity of CAFs." (PMID 29996493, 2018). "Loss of heterozygosity involving the tumor wild type EGLN1 allele suggests that EGLN1 may act as tumor-suppressor gene." (PMID 24899893, 2014). "These mice showed the same primary tumor growth as EGLN1 wild type, but decreased metastases due to reduced CAFs activation and improved blood vessels." (PMID 41413686, 2025). "The EGLN1 gene has been shown to have a key role in regulating the response to hypoxia in these populations, supporting various pro-oncogenic or tumor-suppressive functions." (PMID 41413686, 2025). "Hypoxia-inducible factor 1-alpha (HIF1A) is a key transcription factor aiding tumor cells’ adaptation to hypoxia, regulated by the prolyl hydroxylase family (EGLN1-3) by directing toward degradation pathways." (PMID 38928200, 2024). "Specifically, tumors with high expression of genes such as FTH1, EGLN1, and BCPB1 had more microbiomes associated with tumor metastasis." (PMID 36672459, 2023). "Firstly, endothelial cells showed decreased expression of mouse Angpt2 and Egln1 genes, which typically promote tumor cell metastasis and the dysregulation of vascular stability." (PMID 37660083, 2023). "We found that the expression of EGLN1 showed a positive correlation with tumor T classification and clinical staging of patients with NPC." (PMID 35517429, 2022). "The qPCR results revealed that the mRNA levels of RRM2, MIF, PANX1, and EGLN1 were significantly higher in tumor samples than in paired normal samples." (PMID 35311093, 2022). "This includes EGLN1, a well described cancer gene involved in regulation of tumor hypoxia, and CDC42, an oncogene involved in cell cycle control." (PMID 30894871, 2019). "Both tumor-promoting and suppressive roles of EGLN1 have been reported in different types of cancer." (PMID 30662454, 2018). "Two possible candidate tumor suppressor genes located within the deleted segment are FH (fumarate hydratase) and EGLN1 (EGL nine homolog 1), implicated in other types of tumors." (PMID 23341988, 2013). "EGLN1 haplodeficiency induces vasculature normalization and enhances tumor oxygenation in mice." (PMID 41413686, 2025). "Genetic deletion of EGLN1 in T lymphocytes increases EG7-OVA tumor-killing activity." (PMID 41413686, 2025). "EGLN1, in particular, has been described as a tumor suppressor in colorectal and pancreatic cancer, as a pro-oncogenic factor in acute myeloid leukemia and in lung and ovarian carcinoma, and as having dual roles depending on the study in breast and hepatocellular carcinomas." (PMID 41413686, 2025). "EGLN3 is a tumor suppressor in most cases, whereas EGLN1 and EGLN2 have more controversial roles." (PMID 41413686, 2025). "Moreover, in a syngeneic model of cancer growth, EGLN1 haplodeficiency in host cells induces the normalization of the endothelial cell lining, leading to improved tumor oxygenation and drug diffusion, and to decreased metastatization." (PMID 41413686, 2025). "Moreover, we observed significantly lower EGLN1 mRNA levels in tumor tissues in both age groups (above and under 60 years old), female patients, and different T and N tumor stages and grades." (PMID 38928200, 2024). "We found significantly higher mRNA levels of EGLN3, HIF1A, GLUT1, VEGF, and CA9 (p = 0.021; p < 0.0001; p < 0.0001; p = 0.004, and p < 0.0001, respectively) genes in tumor tissues compared to normal ones and downregulation of the EGLN1 mRNA level in tumor tissues (p = 0.0013)." (PMID 38928200, 2024).
tumor (continued). "Upregulation and stabilization of HIFs is widely associated with angiogenesis, tumor progression, and immune evasion in various tumors, and HIFs are crucial for mediating the tumorigenic effects of mutated VHL, SDHx, and EGLN1 in PCC and PGL." (PMID 36699028, 2022). "As we expected, EGLN1 promoted the capability of tumor sphere formation of CNE2." (PMID 35517429, 2022). "Indeed, findings from heterozygous HIF-prolyl hydroxylase-2 +/− (PHD2/EGLN1+/−) mice support this by showing an improved vessel architecture within the tumor but reduced metastasis upon transplantation of PHD2/EGLN1+/+ tumor cells compared to wild-type mice." (PMID 31083568, 2019). "Similarly, silencing of EGLN1 was shown to reduce the ability for tumor sphere formation." (PMID 35517429, 2022). "To determine the DNA methylation status of EGLN1-3 and HIF1A promoter regions in both tumor and normal tissues in our patient cohort (n = 77), we used methylation-sensitive High-Resolution Melting Analysis (MS-HRM)." (PMID 38928200, 2024). "To investigate potential differences in DNA methylation between tumor and adjacent normal tissues based on TCGA data, we utilized the UALCAN database to visualize promoter DNA methylation status in HIF1A and EGLN1-3 genes among HNSCC patients." (PMID 38928200, 2024). "We assessed the hypoxia-related gene expression (HIF1A, EGLN1-3, CA9, GLUT1, VEGF) by qPCR in our study group of 96 tumor tissues and 96 adjacent normal tissues of HNSCC patients." (PMID 38928200, 2024). "To further elicit better predictors amongst the range of PD-L1 expression in tumor tissues, we grouped the samples based on three genetic backgrounds: sporadic cases, pseudohypoxia cluster (SDHB, VHL, EGLN1, EPAS1) and kinase signaling cluster (RET, NF1)." (PMID 36439433, 2022). "Of the remaining 41 genes, three (PIGC, PKM and PPIB) were commonly upregulated with oncogenic potential and 31 were commonly downregulated among CP and PDAC-CP, of which, 3 (AZGP1, EGLN1 and GNMT) were tumour suppressors." (PMID 35854233, 2022). "EGLN1, MIF, PANX1, and RRM2 showed a consistently high expression in 15 tumor samples compared to paired normal tissues." (PMID 35311093, 2022). "Egl-9 family hypoxia inducible factor 1 (EGLN1) was a key cellular oxygen sensor, which played important roles in tumor angiogenesis and tumor metastasis." (PMID 30662454, 2018). "The first cluster contains pseudohypoxia-driven tumours including VHL, SDH, EGLN1 and HIF2A mutant tumours." (PMID 29166454, 2017). "EGLN1, MIF, PANX1, and RRM2 had higher expression in tumor than in normal samples." (PMID 35311093, 2022). "Our data also suggest that EGLN1 and S100A2 are likely to act at later stages of the metastatic cascade (extravasation, seeding, survival, and/or growth of the tumor cells in secondary sites) because, although the primary tumors are very invasive, they failed to colonize distant organs." (PMID 24618895, 2014). "Nitric oxide and Rgs5 have been revealed as key regulators and the haplodeficiency of Egln1 within host mice (i.e. not within engrafted tumor cells) also influenced intra-tumor capillary structure." (PMID 22905089, 2012). "However, in our analysis, we did not detect significant differences between tumor and normal tissues at the EGLN1 protein level, probably due to the limited sample size." (PMID 38928200, 2024). "In addition, 3 tumour suppressors genes were down regulated: GNMT, AZGP1 and EGLN1." (PMID 35854233, 2022). "They thus proposed that EGLN1 regulated tumor aggressiveness independent of the HIF1α pathway." (PMID 35517429, 2022). "Moreover, hsa-miR-532-5p, RBM38, EGLN1, and DLEU1 were demonstrated as both oncogenes and tumor-suppressors in non-CESC cancers and their roles in CESC were unclear." (PMID 30662454, 2018).
tumor (continued). "Cells in which CYR61, EGLN1, or S100A2 were knocked down formed highly invasive (white arrow) and desmoplastic tumors resembling the control tumors, suggesting that these proteins did not influence tumor invasion or fibrosis." (PMID 24618895, 2014).